SLC45A2 (solute carrier family 45 member 2)
Description:
Proton-associated glucose and sucrose transporter (By similarity). May be able to transport also fructose (By similarity). Expressed at a late melanosome maturation stage where functions as proton/glucose exporter which increase lumenal pH by decreasing glycolysis. Regulates melanogenesis by maintaining melanosome neutralization that is initially initiated by transient OCA2 and required for a proper function of the tyrosinase TYR.
Synonyms: AIM1; MATP; AIM-1; OCA4; 1A1; SHEP5
Tractability: Antibody: UniProt predicts a signal peptide or a membrane-spanning region.
Gene: Protein-coding gene on chromosome 5 (33,944,623 to 33,984,693, reverse strand). Ensembl gene ENSG00000164175.
Subcellular location: Melanosome membrane
Pathways (Reactome):
Metabolism: Melanin biosynthesis
Gene Ontology:
Molecular function: D-glucose:proton symporter activity; sucrose:proton symporter activity; transmembrane transporter activity
Biological process: lysosomal lumen pH elevation; melanin biosynthetic process from tyrosine; developmental pigmentation; sucrose transport; hexose transmembrane transport; transmembrane transport
Cellular component: melanosome membrane
Genetic constraint (gnomAD): Loss-of-function variants: 37 observed, 47.63 expected, observed/expected ratio (o/e) 0.78, 90% interval 0.6 to 1.02. The upper end of that interval is the gene's LOEUF score, 1.02, which puts it in group 4 of 6, group 1 being the genes least tolerant of losing a copy. Missense variants: 719 observed, 707.49 expected, observed/expected ratio (o/e) 1.02, 90% interval 0.95 to 1.08. Synonymous variants: 306 observed, 285.62 expected, observed/expected ratio (o/e) 1.07, 90% interval 0.98 to 1.18.
Homologues: Orthologues: chimpanzee SLC45A2 (99% identical), macaque SLC45A2 (96% identical), rabbit SLC45A2 (86% identical), guinea pig SLC45A2 (84% identical), rat Slc45a2 (83% identical), mouse Slc45a2 (82% identical), pig SLC45A2 (69% identical), tropical clawed frog slc45a2 (69% identical), dog SLC45A2 (68% identical), zebrafish slc45a2 (61% identical), Drosophila melanogaster lovit (31% identical), Drosophila melanogaster Slc45-1 (29% identical). Paralogues in human: SLC45A1 (40% identical), SLC45A4 (37% identical), SLC45A3 (23% identical).
Diseases named in the same sentence as SLC45A2 in open-access papers:
SLC45A2 is named in the same sentence as 53 diseases in open-access papers, as found by Europe PMC text mining. Sharing a sentence is not in itself a finding about the gene and the disease. The quoted sentences say what the papers report.
melanoma (57 papers, 2010 to 2025). A malignant, usually aggressive tumor composed of atypical, neoplastic melanocytes. "In our previous study, haplotype analyses of CDKN2A and SLC45A2 were significantly associated with melanoma risk in Colombian patients." (PMID 40429816, 2025). "As for TYR (OCA1) and SLC45A2 (OCA4), patients with these mutations showed an irregular pigmentation as the most characteristic dermoscopic aspect of melanomas, despite the common tendency to develop hypomelanotic/amelanotic lesions, as previously reported." (PMID 37568588, 2023). "Although sequence variations in SLC25A4 and SLC45A2 have been described as associated with skin hypopigmentation and a higher risk for melanoma, their gene regulation mechanism is still unclear and should be further investigated." (PMID 37397501, 2023). "Using this method, we have identified and validated peptides associated with the melanoma differentiation antigen SLC45A2 as shared melanoma-associated tumor targets and have generated TCRs recognizing these peptides." (PMID 34572028, 2021). "to detect and characterize gene-gene interactions among HERC2 (rs1129038), SLC24A5 (rs1426654), and SLC45A2 (rs16891982) in risk of developing melanoma." (PMID 33167923, 2020). "This gene encodes SLC45A2, which is a transporter highly expressed in the melanosomal membrane of melanocytic cell lines, where it is overexpressed in melanoma cells." (PMID 28300201, 2017). "The SNP rs6059655, intergenic near RALY-ASIP, is associated with facial pigmentation spots and rs35407 (SLC45A2), is associated with pigmentation and melanoma risk." (PMID 28212542, 2017). "Another example is the genes related to melanoma, as they are also associated with skin color, eye color and albinism (SLC45A2), preterm birth (DHCR7), and Vitamin D levels (NADSYN1)." (PMID 27042214, 2016). "We recently reported a sex difference in association with melanoma for rs16891982 in SLC45A2, another SNP in a solute-carrier gene associated with pigmentation." (PMID 25789475, 2015). "The correlation of the rs16891982 SNP in the SLC45A2 gene with melanoma was used as a case study for analysis of disease risk, and the results were consistent with the incidence and mortality rates of melanoma in published scientific literature." (PMID 23786662, 2013). "In population-based studies using candidate-gene approaches, a solute carrier 45A2 (SLC45A2) variant was associated with dark hair, dark skin, and protection from melanoma." (PMID 23537197, 2013). "SLC45A2 has earlier been associated with melanoma only in the context of pigmentation, where mutations in the gene confer higher melanoma risk." (PMID 22693581, 2012). "A novel SNP located on the SLC45A2 gene (rs35414) was found to be significantly associated with melanoma in both phase I and phase II (P<0.0001)." (PMID 21559390, 2011). "Notably, SLC24A5 and SLC45A2 genes encode for melanosome-associated transporters both involved in melatonin synthesis in melanocytes and melanoma cells." (PMID 37397501, 2023). "The presence of homozygous genotypes of either SNP (AA for rs1426654 and AA for rs1129038) were associated with increased melanoma risk, while the SLC45A2 rs16891982 C allele was associated with protection for melanoma in a GWAS study in Greece composed of 284 patients and 284 controls (OR = 0.51." (PMID 33167923, 2020). "Finally, SNPs SLC24A5 rs1426654 and SLC45A2 rs16891982 were associated with fair skin, eyes, and hair and with melanoma." (PMID 33167923, 2020). "It is unclear whether other common variants that have been associated with melanoma, particularly other pigmentation genes, such as SLC45A2, TYR or TYRP-1, may also exhibit a similar modifying effect CDKN2A penetrance similar to MC1R." (PMID 29774366, 2018). "Interestingly, it was recently reported that the positively selected gene SLC45A2 was also associated with melanoma susceptibility in a South European population, thus underlining the important link between selection and diseases." (PMID 26553317, 2015).
melanoma (continued). "As such, variants in other ion transport genes similar to TPCN2 and SLC45A2 might also be expected to impact pigmentation and melanoma risk." (PMID 25789475, 2015). "Furthermore, the involvement of genetic variants of SLC45A2 in melanoma susceptibility is also being investigated." (PMID 25093503, 2014). "Furthermore, individuals carrying two or more mutations in MC1R, a well-known low penetrance melanoma-predisposing gene, had a decreased MM risk if concurrently bearing the SLC45A2 protective variant." (PMID 21559390, 2011). "Similarly to other ion transport genes associated with melanoma, such as SLC45A2, variants in TPCN2 may impact melanogenesis through pH regulation." (PMID 25789475, 2015). "The SLC45A2 gene is involved in melanin production and, hence, affects pigmentation and is highly expressed in melanoma cell lines." (PMID 39940926, 2025). "Many well-known pigmentation genes were among the 150 most upregulated genes in the intradermal melanomas: Slc45a2, Tyrp1, Tyr, Pmel, Dct, Oca2, Mlana, Slc24a4, and Mc1r." (PMID 39804140, 2025). "Eight (10%) patients were identified that carried pathogenic mutations in known melanoma predisposition genes POT1, MITF, OCA2, SLC45A2 and TYR." (PMID 39315505, 2025). "Among the genes we identified, many are known melanoma susceptibility genes including CASP8, ARNT, and OCA2 (downregulated), PARP1, SETDB1, MTAP, SLC45A2, and MC1R (upregulated), and MX2 (both up‐ and downregulated)." (PMID 38308491, 2024). "It has been previously demonstrated that the proton/glucose exporter SLC45A2 mediates melanin synthesis and melanoma metastasis primarily by modulating melanosomal glucose metabolism." (PMID 37627399, 2023). "In vitro, antigen-specific CTLs generated against HLA-A*02:01 and HLA-A*24:02-restricted SLC45A2 peptides were shown to kill most HLA-matched melanoma cells lines, including uveal melanoma cells." (PMID 35267523, 2022). "Compared to other melanocytic proteins, such as MART-1 and PMEL, the expression of SLC45A2 in normal melanocytes was shown to be less than 2%, resulting in a significantly improved melanoma-to-melanocyte CTL killing index." (PMID 35267523, 2022). "SLC45A2 (as also AIM1 or MATP) encodes a transporter protein that mediates melanin synthesis, which is expressed in a high percentage of melanoma cell lines." (PMID 34238381, 2021). "The final 83 pathogenic/likely pathogenic (P/LP) germline variants (66 unique) in 71/264 (26.8%) melanoma patients were detected in 42/217 targeted genes and included five copy number variants (CNV; two in CHEK2 and SLC45A2, respectively, and one in TRPM1)." (PMID 33050356, 2020). "The contribution of the other two markers, SLC45A2 rs16891982 (3.80%) and HERC2 rs1129038 (2.34%), indicated that they also have an important role in predicting melanoma risk." (PMID 33167923, 2020). "This study assessed previously reported coding variants in albinism genes (TYR, OCA2, TYRP1, SLC45A2, SLC24A5, LRMDA) and common intronic, regulatory variants of OCA2 in individuals with amelanotic/hypomelanotic melanoma, pigmented melanoma cases and controls." (PMID 32966289, 2020). "SLC45A2 has been related to melanin synthesis and it is highly expressed in melanomas, a cancer type sensitive to MEK inhibitors." (PMID 30245630, 2018). "Among the SLC45A members, the SLC45A2 transcript was highly enriched in the majority of the melanoma cell lines." (PMID 26057890, 2015). "The SLC45A2 gene is highly enriched in human melanocytes and melanoma cell lines, and its protein, MATP, is located in melanosomes." (PMID 26057890, 2015). "Though they transport different molecules, these SNPs in SLC45A2 and near TPCN2 both demonstrated associations with melanoma that were larger in males than in females." (PMID 25789475, 2015). "Among SLC45A family genes, only SLC45A2 was enriched in the tested human melanocytes and melanoma cells and its protein, MATP, was located in melanosomes." (PMID 26057890, 2015).
melanoma (continued). "Additional pigmentation-related genes associated with melanoma risk are tyrosinase (TYR); tyrosinase-related protein 1 (TYRP1); solute carrier family 45, member 2 (SLC45A2); and solute carrier family 24, member 4 (SLC24A4)." (PMID 24392023, 2013). "The role of SLC45A2 in melanoma predisposition was further analyzed in relation to MC1R, the main low penetrance gene associated to melanoma." (PMID 21559390, 2011). "TCR-T therapies have been developed to target a range of melanoma-associated antigens expressed in UM, including PRAME (preferentially expressed antigen in melanoma), MAGE-C2 (melanoma-associated antigen C2), SLC45A2, and MART-1 (melanoma antigen recognized by T cells-1)." (PMID 40725830, 2025). "Moreover, knockdown of SLC45A2 in a pigmented melanoma cell line resulted in increased acidification of early-stage melanosomes." (PMID 37943814, 2024). "In our cohort, out of 115 patients referred to genetic counseling for melanoma, 25 tested positive (21.7%) for critical mutations: CDKN2A (n = 12), MITF (n = 3), BAP1 (n = 1), MC1R (n = 3), PTEN (n = 1), TYR (n = 2), OCA2 (n = 1), and SLC45A2 (n = 2)." (PMID 37568588, 2023). "In particular, retinal density– and FD-lowering alleles at several PoPS-prioritized genes showed associations with higher risk of skin neoplasms, malignant melanoma, and eye cancer (IRF4/DUSP22, SLC45A2); a separate set of loci showed associations with lighter skin color (GNB2, ACTG1)." (PMID 34743558, 2022). "Both SLC12A9 and SLC45A2, which we associate with melanoma and non-melanoma skin cancer, are implicated with pigmentation according to the Open Targets Platform62." (PMID 34290314, 2021). "The combination of SLC24A5 rs1426654AA and SLC45A2 rs16891982GG was significantly associated with melanoma risk regardless of the genotype of HERC2 rs1129038, confirming the lower weight of HERC2 (2.34%) in the analysis of gene interaction." (PMID 33167923, 2020). "In this case-control study conducted in Southern Brazil, SNPs SLC24A5 rs1426654 and SLC45A2 rs16891982 were associated with an increased risk for melanoma, which was found to be additive and independent of pigmentation profile." (PMID 33167923, 2020). "Expression of FAM174B, MAD1L1, SCARB1, MFSD12, SEMA6A, SLC45A2, and TBC1D16 was found to be upregulated and associated with worse OS in melanoma patients, while only MFSD12 and SLC45A2 were associated with worse DFS for melanoma patients." (PMID 30385854, 2019). "By these analyses, we showed that upregulated MFSD12 and SLC45A2, which were associated with OS and DFS, may play an important role in melanoma." (PMID 30385854, 2019). "Interestingly, in human cells, the SLC45A2 gene of the SLC45 family is highly enriched in melanocytes and melanoma cell lines, and its protein, MATP, is located in melanosomes, implying a role for the sucrose transporter MATP in melanin synthesis." (PMID 27092497, 2016). "In humans, a nonpathogenic SNP located in an intronic region of SLC45A2 has been identified in which the major allele is significantly associated with malignant melanoma and the minor allele is protective." (PMID 24647637, 2014). "However, other melanoma differentiation antigens such as SLC45A2 show much lower levels of expression in normal tissues, which may reduce the risk of autoimmune side-effects." (PMID 34572028, 2021). "Out of 20 orthologues of human melanoma-associated loci, 12 contained SNPs with p-values < 10–2 in the MeLiM model, and 6 of them had SNPs reaching a p-value < 10–3: CDKAL1 on SSC7, FTO on SSC6, PLA2G6 on SSC5, TMEM38B-RAD23B on SSC1 and SLC45A2 and TERT on SSC16." (PMID 29963229, 2018). "The Kaplan–Meier analysis showed that five upregulated genes were significantly related to both the OS and DFS of melanoma patients, including TUBB4A, PSEN2, SLC45A2, QPRT, and TRPV2." (PMID 37439014, 2023). "In human melanocytes and melanoma cell lines, the SLC45A2 gene is highly enriched, and MATP, the gene’s protein, is found in melanosomes." (PMID 37627399, 2023).
melanoma (continued). "According to these results, the best model for predicting melanoma development was the combination of the three factors (HERC2 rs1129038, SLC24A5 rs1426654, and SLC45A2 rs16891982)." (PMID 33167923, 2020). "Few high penetrance genes are known in Malignant Melanoma (MM), however, the involvement of low-penetrance genes such as MC1R, OCA2, ASIP, SLC45A2 and TYR has been observed." (PMID 23537197, 2013). "Recent GWAS have unveiled association between SNPs or genetic variants in MC1R, TPCN2, ASIP, KITLG, SLC24A5, TYR, IRF4, OCA2/HERC2, SLC24A4, SLC45A2, TYRP1, and pigmentation as well as melanoma." (PMID 21559390, 2011). "Receiver operating characteristic (ROC) curves showed an area under the curve (AUC) >90.0% for KPNA2, DTL, BACE2, DTYMK, E2F3 and SLC25A13, >80.0% for CCNA2, FOXM1, KIF4A, SLC45A2, COPS8, SLC45A13 and 70.0% for CDC25A and LINC00520; all significantly discriminating melanoma from benign nevi." (PMID 36320118, 2022). "Oddly, both MFSD12 and SLC45A2 belong to the major facilitator superfamily, indicating that MFS may play important roles in melanoma." (PMID 30385854, 2019). "Similarly, MAGE-C2, expressed in 39% of melanomas and absent in normal tissues, and SLC45A2, a melanocyte lineage antigen highly expressed in UM cell lines but minimally in normal tissues, have also been validated as effective TCR targets." (PMID 40725830, 2025). "Furthermore, by using RNA-seq data from The Cancer Genome Atlas (TCGA) melanoma cohort, we found that the mRNA level of UFL1 was negatively correlated with those of well-known targets downstream from melanin biosynthesis pathway, including OCA2 and SLC45A2." (PMID 36120581, 2022).
albinism (32 papers, 2007 to 2024). A congenital disorder characterized by partial or complete absence of melanin pigment in the eyes, hair, or skin. "The concomitant diagnosis of SLC45A2-associated albinism due to UPD was pertinent to genetic counseling for the family." (PMID 39282052, 2024). "Mutations in SLC45A2 gene are a cause of a form of albinism, and polymorphisms in this gene are associated with variations in pigmentation traits (skin and hair color) and tanning ability." (PMID 38182794, 2024). "In the total study population, four common variants of known albinism genes were detected with high frequencies: the L374F variant of the SLC45A2 protein, the R305W of the OCA2 protein and the R402Q and S192Y TYR proteins." (PMID 38279271, 2024). "Mutations in SLC45A2 can affect the processing of tyrosinase, causing albinism in human eyes and skin." (PMID 32703156, 2020). "Although the candidate gene SLC45A2 is known to be involved in albinism in different species, to date in cattle only mutations in the TYR and MITF genes were reported to be associated with albinism or albinism-like phenotypes." (PMID 28982372, 2017). "We found a private non-synonymous substitution in one of the candidate genes - the SLC45A2 gene - associated with the OCA4 class of albinism." (PMID 23721540, 2013). "Mutations in the SLC45A2 gene have been reported in albinism in humans." (PMID 36683094, 2023). "Conclusively, molecular and in silico analyses of identified mutations in TYR and SLC45A2 protein provide the pathogenicity prediction as well as structural and functional changes that are likely to confirm the contribution to pathogenesis of albinism." (PMID 32849781, 2020). "Molecular genetic diagnosis for most patients started with a next-generation sequencing (NGS) panel targeting genes associated with albinism—TYR, OCA2, MC1R, MITF, SLC45A2, TYRP1, and GPR143—as the initial clinical diagnosis for all patients was albinism." (PMID 39457042, 2024). "Molecular studies identified seven genes linked to the OCA phenotype (TYR, OCA2, TYRP1, SLC45A2, SLC24A5, C10orf11, and DCT) and one locus (OCA5) in consanguineous and sporadic albinism." (PMID 35741834, 2022). "The present computational analysis provides a theoretical basis for the molecular mechanism of albinism underlying TYR and SLC45A2 gene mutations." (PMID 32849781, 2020). "Overall, this study will contribute to further studies of disease prevention and treatment of TYR- and SLC45A2-related albinism." (PMID 32849781, 2020). "Oculocutaneous albinism 2 (OCA2) and solute carrier 45 member 2 (SLC45A2, also known as MATP, membrane-associated transporter protein, or OCA4) are known to be the causative gene products of oculocutaneous albinism." (PMID 32595944, 2020). "The abnormal development of melanocytes drives albinism; hence, we consider Slc45a2 as a candidate gene on the basis of its involvement with other aspects of neural crest development." (PMID 25790447, 2015). "First of all, this study demonstrates that the sequencing of whole genes, as we did here with our current diagnostic panel that contains the entirety of five major albinism genes (TYR, OCA2, SLC45A2, GPR143 and HPS1), is instrumental in identifying deep intronic splice variants in these genes." (PMID 39201349, 2024). "During melanosome maturation, the melanosomal pH is modulated owing to the activity of membrane transport proteins such as SLC45A2, OCA2/P, TPC2, the Cl−/H+ exchanger CLC-7 mutated in a subset of albinism patients and possibly other still unidentified Ca2+ channels." (PMID 34921635, 2021). "The most common cause of foveal hypoplasia is albinism, but no mutations were identified in SLC45A2, TYR, TYRP1, GPR143, OCA1, OCA2, OCA3, or OCA4." (PMID 28546991, 2017).